COL3A1 (collagen type III alpha 1 chain)
Diseases named in the same sentence as COL3A1 in open-access papers (continued):
Sharing a sentence is not in itself a finding about the gene and the disease.
pulmonary fibrosis (32 papers, 2013 to 2025). Chronic progressive interstitial lung disorder characterized by the replacement of the lung tissue by connective tissue, leading to progressive dyspnea, respiratory failure, or right heart failure. "However, the associations of these genes in liver are not as strong as in the lung—possibly indicating these molecular events are limited to SSc-related progressive lung fibrosis in case of the mutation of COL3A1 in human." (PMID 26444860, 2015). "At 21 d.p.i., deletion of both Yap and Taz in myofibroblasts strongly attenuated lung fibrosis and suppressed the expression of key myofibroblast activation and profibrotic genes, including Acta2, Col1a1, Postn, Fn1, Col3a1, and Tgfb1." (PMID 40454481, 2025). "The massive secretion of COLGALT1 in macrophages promoted the galactose modification of COL3A1, thus further aggravating the pulmonary fibrosis cascade." (PMID 39083563, 2024). "During lung fibrosis, the expression of Acta2 and collagen 1a1 (Col1a1) and 3a1 (Col3a1) in the PDGFR-β+ cell lineage is markedly increased." (PMID 34893592, 2021). "We further found that lung fibrosis and the expression of fibrosis genes, including Col1a1, Col3a1 and Fn1, an outcome mediated by the accumulation of senescence, were reduced by SSK1 treatment." (PMID 32341413, 2020). "The lung fibrosis was examined by Masson’s trichrome (MT) stain of paraffin sections and mRNA expression levels of Col1a1, Col3a1, and Acta2 in different frozen lung samples." (PMID 29497425, 2018). "Also, FPNI treatment prevented the upregulation of senescence markers that are well-known to be associated to lung fibrosis, such as TNF-α, Il6, Cdkn1a and Cdkn1b along with that of collagen isoforms Col1a1 and Col3a1." (PMID 38167804, 2024). "However, the inactivation of Yap1 by itself in AT2 cells resulted in increased AT2 to AT1 cell differentiation and decreased pulmonary fibrosis based on hydroxyproline content and significantly less Col1a1 and Col3a1 RNA expression." (PMID 37166104, 2023). "The increase in Col3a1 expression and changes in collagen-I:collagen-III ratio alter the collagen-I microstructure and are implicated in the production of therapeutic resistance to corticosteroids in pulmonary fibrosis." (PMID 34830342, 2021). "A previous study showed that miR-196a directly regulated Col1a1 and Col3a1 expression in keloid fibroblasts 46, and miR-196a/Col1a1 has been reported to participate in pulmonary fibrosis 47, though its roles in CFs and cardiac fibrosis remain unknown." (PMID 34158869, 2021). "Notably, LAM MACs were similar to the fibroblasts identified in pulmonary fibrosis, which also express COL3A1, COL1A1, and ACTA233." (PMID 33159078, 2020). "However, deficient autophagy in this model enhanced lung fibrosis, which was characterized by upregulation of collagens, COL1A2 and COL3A1." (PMID 28424691, 2017). "Increased levels of lysyl oxidase (LOX), an amine oxidase critical for the initiation of collagen and elastin cross-linking, increased mRNA levels of collagen type I (Col1a2), collagen type III (Col3a1) and matrix metalloproteinase (Mmp2) have been reported in murine models of lung fibrosis." (PMID 24204629, 2013). "However, studies for COL3A1, which encodes for collagen 3A1, have shown that expression of this gene is positively regulated by SPP1 in a murine model of asbestos-induced lung fibrosis and that over-expression of the gene is linked to fibrosis and tissue remodeling." (PMID 25248511, 2014). "MiR-26a functions as an endogenous inhibitor of the TGF-β1/Smad signaling pathway, and its downregulation in IPF and pulmonary fibrosis mice models leads to the upregulation of CTGF, COL1A1, and COL3A1." (PMID 39479511, 2024). "Further detection results of pulmonary fibrosis-related markers showed that PDGF-BB induction increased the expression levels of major ECM components, including COL1A1, COL3A1, LN, FN, and α-SMA." (PMID 37138491, 2024).
pulmonary fibrosis (continued). "Overexpression of miR-27b in lung fibrosis mice and LL29 cells was found to suppress the expression of COL1A1, COL3A1, COL4A1, and α-SMA induced by TGF-β1, thereby reducing cellular contractility." (PMID 39479511, 2024). "A decrease in Let-7d expression induces an increase in COL3A1 and SMAD2 expression, which are involved in the development of pulmonary fibrosis." (PMID 36012303, 2022). "In contrast, we find an enrichment of several markers of pulmonary fibrosis (CLU, COL1A1, COL1A2, and COL3A1) in SARS-CoV-2-low patients (these correspond to the later stages of infection), indicating that there are two distinct stages of infection." (PMID 35233546, 2022). "HuR appears to function via direct binding to mRNAs for COL1A1, COL3A1, ACTA2, and FN, and it was found that HuR is localized to a greater degree in the cytosol in cells from mouse lung fibrosis models as well as human idiopathic pulmonary fibrosis patients." (PMID 35892569, 2022). "Extracellular matrix protein and gene expression of markers involved in lung fibrosis (tenascin-c, fibronectin, collagen I [COL1A1], collagen III [COL3A1] and α-smooth muscle actin [α-SMA]) were analyzed." (PMID 29703175, 2018). "In this study, we investigated SAHA’s effects on the expression of collagen III alpha 1 (COL3A1) in primary human IPF fibroblasts and in a murine model of pulmonary fibrosis." (PMID 24084714, 2013). "The increased transcripts of col1a2 and col3a1 and protein level of α-SMA showed that the lung fibrosis aggravated after BLM treatment and peaked around the 3rd week." (PMID 23476100, 2013). "ADAR1-p110 and ADAR1-p150 regulate the processing of the pri-miR-Let-7d and mature Let-7d in such a way that the sub-expression of the latter deregulated, in turn, the expression of COL3A1 and SMAD2, proteins involved in the development of idiopathic pulmonary fibrosis." (PMID 36012303, 2022). "Consistent with the induction of lung fibrosis by BLM, the transcript expression levels of various fibrogenic protein genes including Col1a1, Col3a1, Eln, Fn, Ctgf, as well as Txndc5, were significantly upregulated in BLM-treated mouse lungs (21 days post-BLM treatment)." (PMID 32848143, 2020). "Similarly, we find enrichment of several markers of pulmonary fibrosis (CLU, COL1A1, COL1A2, and COL3A1) in SARS-CoV-2-low samples as compared with nonviral and viral ARDS samples, exemplifying the profound lung injury and fibrosis during later stages of COVID-19." (PMID 35233546, 2022).
Myocardial fibrosis (30 papers, 2014 to 2025). "Numerous studies have highlighted the association between an elevated Col1a1/Col3a1 ratio and myocardial fibrosis." (PMID 39592912, 2025). "Fibrotic and extracellular remodeling markers Tgfβ1, Mmp2, Timp1, Col1a1, Col3a1, fibronectin and vimentin demonstrated a complex balance underlying myocardial fibrosis at different overload stages." (PMID 31181097, 2019). "We found that tRF-Glu-CTC-013 reduced the expression of Tgfb1, Col1a1, Col3a1 and Fn1, thereby inhibiting myocardial fibrosis." (PMID 40520901, 2025). "The myocardial fibrosis marker gene Col1a1, Col3a1, and Tgfb1 were downregulated, correlated with the reversal of Piezo1." (PMID 40344385, 2025). "Treatment with miR-214-3p agomir reduced the myocardial expression of COL1A1 and COL3A1 and attenuated myocardial fibrosis in mice." (PMID 41166051, 2025). "For example, in mice with myocardial fibrosis post‐myocardial infarction, Col1a1 levels were significantly increased, whereas Col3a1 levels decreased, resulting in an elevated Col1a1/Col3a1 ratio." (PMID 39592912, 2025). "Targeting proteins directly involved in collagen synthesis, such as collagen type l alpha (COL1A1) and COL3A1, is an alternative way of targeting excessive collagen synthesis in myocardial fibrosis." (PMID 41166051, 2025). "Histological analyses by Sirius red staining showed exaggerated myocardial fibrosis in Gadlor-EV-treated mice, which was confirmed by qPCR of Col1a1 and Col3a1 mRNA expression in the myocardium." (PMID 39281699, 2024). "Combining these findings with our study results, it is suggested that Fmod may contribute to myocardial fibrosis in RCFs by increasing the Col1a1/Col3a1 ratio, thereby implicating Fmod in the pathological process of diabetic cardiomyopathy." (PMID 39592912, 2025). "Meanwhile, the upregulated mRNA levels of FN, CTGF, Col1a1 and Col3a1 in the TAC + rAAV9‐miR + SRI group further indicated that SRI‐011381 administration significantly reversed the inhibitory effect of rAAV9‐POSTN‐miR‐425‐5p on myocardial fibrosis." (PMID 39527465, 2024). "The comparison between the T1DM and T2DM mice revealed an increase in myocardial fibrosis in the first group of animals, as confirmed with RT-PCR on freshly isolated CMs, in which the expressions of Col1a1, Col1a2 and Col3a1 were found to be higher in the T1DM mice compared to in the T2DM mice." (PMID 36674648, 2023). "Importantly, our study demonstrated that Fmod overexpression in RCFs elevated the Col1a1/Col3a1 ratio, which may better elucidate how Fmod influences myocardial fibrosis." (PMID 39592912, 2025). "The aggravated cardiac dysfunction and myocardial fibrosis were further supported by increased mRNA levels of ANP, BNP, Col1a1, and Col3a1 in RTN3CKO mice treated with J2." (PMID 38420163, 2024). "While a neutralizing antibody against IL-22 led to increased COL1-A1, COL3-A1, MMP9 expression, and intensified myocardial fibrosis in DCM mice, suggesting that IL-22 protects the myocardium by inhibiting myocardial fibrosis." (PMID 36827455, 2023). "Some studies on the mechanism by which Stat3 exacerbates myocardial fibrosis showed that Stat3 is bound with COL1A1 and COL3A1 promoter and activates their transcription." (PMID 37891701, 2023). "In addition to the obvious myocardial fibrosis observed by histopathology, the mRNA expression of profibrotic TGF-β, CTGF, Col1a1 and Col3a1 were elevated in piglets and cardiomyocytes with MYH7 R453C mutation." (PMID 38862020, 2024). "Moreover, our results revealed that berberine dose‐dependently reduced myocardial fibrosis, which was supported by a decrease in fibrosis area and reduced expression of fibrosis‐related markers (COL1A1, COL3A1, TGF‐β and α‐SMA)." (PMID 38894630, 2024). "Histological analyses revealed increased myocardial fibrosis in Musclin KO mice in response to TAC compared to WT mice, which was accompanied by upregulation of pro-fibrotic genes like Postn, Col1a1, Col3a1 and Fn1." (PMID 35013221, 2022).
Myocardial fibrosis (continued). "Consistent with the protective effect ofNAC on cardiac pathophysiological changes, real-time RT-PCR analysis of the mRNAexpressions that related to cardiac hypertrophy and myocardial fibrosis, such asα-MHC, β-MHC, ANP, BNP, Col1a1, Col3a1, Mmp2,and Mmp9, also showed the similar trend." (PMID 27443826, 2016). "Then the myocardial fibrosis increased and survival rate decreased in mice after neutralizing IL-22, accompanied by a decline in Th22 cell number, reduced IL-22, diminished IL-22R expression and increased indicators of myocardial fibrosis such as COL1-A1, COL3-A1, MMP9." (PMID 25547181, 2014). "The mRNA expression levels of collagen (COL1A1 and COL3A1) and α-SMA, which are markers of myocardial fibrosis, were significantly elevated in the Ang II group compared to the saline group, but muscone treatment significantly suppressed the elevated mRNA levels of α-SMA, COL1A1, and COL3A1." (PMID 38158445, 2023). "The expression of different genes related to myocardial fibrosis was assessed in the rat hearts, revealing that at the 3rd week TiO2-NPs instillation the expression of different collagen isoform genes (namely COL1A2, COL3A1, COL4A1) were definitively upregulated in treated animals compared to CTRL." (PMID 31234877, 2019).
Ehlers-Danlos syndrome (26 papers, 2007 to 2026). The Ehlers–Danlos syndromes (EDS) are a clinically and genetically heterogeneous group of heritable connective tissue disorders (HCTDs) characterized by joint hypermobility, skin hyperextensibility, and tissue fragility. "Background/Objectives: Thoracic aortic aneurysms have long been associated with germline mutations such as FBN1, TGFBR2, and COL3A1, which predispose to Marfan, Loeys-Dietz, and Ehlers-Danlos syndromes, respectively." (PMID 42074482, 2026). "Genetic testing revealed a novel missense mutation (c.2095G>T, p.Gly699Cys) in the COL3A1 gene, which is presumed to be a pathogenic variant of vascular Ehlers-Danlos syndrome." (PMID 37171638, 2023). "Vascular Ehlers-Danlos syndrome (vEDS), the most severe type of Ehlers-Danlos syndrome, is caused by an autosomal-dominant defect in the COL3A1 gene." (PMID 38174045, 2023). "vEDS, formerly known as Ehlers-Danlos syndrome type IV, is one of the 13 subtypes of Ehlers-Danlos syndrome 8 and is caused primarily by COL3A1 mutations." (PMID 36700191, 2022). "Polymorphisms in COL1A2 and COL3A1 (which together make up 80–90% of arterial collagens) are well-established in IAs, and are known to lead to Ehlers-Danlos syndrome." (PMID 31666072, 2019). "Loss of COL3A1 function is associated with Ehlers-Danlos syndrome (EDS), where skeletal manifestations include a distinctive facial appearance, scoliosis, and osteoporosis." (PMID 31651232, 2019). "Mutations in the coding region or the intron region of COL3A1 gene leads to an arterial disease termed as Ehlers-Danlos syndrome (EDS) and affects patient survival." (PMID 26741506, 2016). "Genetic testing revealed a heterozygous COL3A1 gene variant associated with Ehlers-Danlos syndrome." (PMID 39539482, 2024). "For example, gene mutation causing systemic diseases such as Marfan syndrome (FBN1), Ehlers-Danlos syndrome (COL3A1), and Loeys-Dietz syndrome (TGFBR1/2) could significantly increase the risk of aortic dissection." (PMID 37596272, 2023). "Moreover, mutation in COL3A1 can be found in more than 95% of patients with Ehlers-Danlos syndrome (EDS) with aortic complications." (PMID 35054350, 2022). "While the pseudoaneurysm and arteriovenous fistula in this patient were initially thought to be traumatic in origin, genetic testing later revealed a mutation in the COL3A1 gene of collagen 3 compatible with a diagnosis of the Vascular (Type 4) Ehlers-Danlos syndrome." (PMID 25349770, 2014). "In the light that Ehlers-Danlos syndrome (EDS) caused by a PV in the COL3A1 gene has an AD inheritance pattern, genetic testing for this variant was recommended in the patient’s first-degree relatives." (PMID 41466732, 2025). "For example, Marfan syndrome and Ehlers-Danlos syndrome are known to cause vascular fragility due to mutations in the FBLN1 and COL3A1 genes associated with elastic and collagen fibers, leading to aortic aneurysms and AD." (PMID 35008739, 2021). "Three genes (COL3A1, COL5A2, and SLC40A1) have also been associated with autosomal dominant disorders (Ehlers-Danlos syndrome classical type, hemochromatosis type 4, and muscle hypertrophy)." (PMID 30911334, 2019). "Variants in COL3A1 and COL5A1, key genes in collagen synthesis and connective tissue integrity, suggest an overlap between SCAD and vascular connective tissue disorders such as Ehlers-Danlos syndrome." (PMID 40815415, 2025). "For instance, mutations in COL1A2, COL3A1, and COL5A2 human genes (identified as hub genes in the present research) are at least in part the genetic basis of the Ehlers-Danlos syndrome: a systemic connective tissue disorder caused by defects in fibrillar collagen deposition." (PMID 35874513, 2022). "Her clinical picture resembles a combination of traits of a hypermobile and a vascular form of Ehlers-Danlos-Syndrome, but no mutations in the COL3A1 gene was underlying." (PMID 22583611, 2012).
ovarian carcinoma (25 papers, 2009 to 2024). A malignant neoplasm originating from the surface ovarian epithelium. "Similar to COL1A1, higher expression of COL3A1 was associated with shorter overall survival in patients with ovarian carcinomas." (PMID 36085041, 2022). "It has been observed that ovarian cancer with a high level of COL3A1 expression was more resistant to chemotherapy." (PMID 35328460, 2022). "The expression of COL3A1 was also observed in ovarian cancer patients and was related to CIS resistance." (PMID 33921897, 2021). "The x-axes depict COL3A1 H-score and the y-axes depict ovarian carcinoma histotype and survival time, wherein the patients have been stratified into four survival groups 0–2 years, 2–5 years, 5–10 years and > 10 years." (PMID 31533654, 2019). "COL3A1 gene has also been found differentially expressed between primary ovarian carcinomas and metastases." (PMID 30448882, 2019). "ECM-receptor interaction was enriched based on the KEGG pathway in our study, while COL3A1, COL5A2, and COL2A1 were regarded as potential ECM components associated with cytostatic drug resistance in ovarian cancer cells." (PMID 28562334, 2017). "The expression of COL3A1, COL5A2, and COL1A2 was also studied by immunocytochemistry and western blot analysis and found to be associated to drug-resistance in ovarian cancer." (PMID 28562334, 2017). "Similarly, in ovarian cancer, overexpressed COL3A1 has been found to promote tumor cell migration and invasion, contributing to disease aggressiveness." (PMID 38913913, 2024). "Similarly, up-regulation of COL3A1 and FN1 has been linked to unfavorable OS in stomach and ovarian cancers, respectively." (PMID 38913913, 2024). "Additionally, COL3A1 has been shown to be a biomarker for ovarian cancers and also its elevated expression reduces the effects of anticancer drugs in vitro." (PMID 37550786, 2023). "COL3A1 was also described as a protein involved in CIS resistance in ovarian cancer." (PMID 32283808, 2020). "Genes COL1A1 and COL3A1 are demonstrated that played an unfavorable role in the development of ovarian cancer, and could be considered as the prognostic genes of OV." (PMID 32429941, 2020). "Moreover, COL3A1, COL5A2 and COL1A2 expression are associated with drug-resistance in ovarian cancer." (PMID 31533654, 2019). "COL3A1 protein expression varied in the 95 RNA sequenced ovarian carcinoma samples." (PMID 31533654, 2019). "In epithelial ovarian cancers, the increase of COL3A1 was prognostic markers of poor prognosis." (PMID 29921304, 2018). "In this module, COL3A1 might be related to ovarian cancer, as it is a known cancer gene targeted by all ovarian cancer miRNAs and belongs to ECM receptor and focal adhesion pathways." (PMID 25611546, 2015). "COL3A1 is also a commonly studied gene in ovarian cancer, where it was revealed that it is one of the most expressed proteins in advanced relative to local ovarian adenocarcinoma, and that its expression was observed to be higher in platinum-resistant relative to platinum-sensitive cells." (PMID 26100469, 2015). "In addition, COL3A1 expression has been related to resistance to platinum drugs in ovarian cancer." (PMID 20043850, 2009). "A previous study also showed that high expression of COL1A1, COL3A1, COL5A1, and COL5A2 in ovarian cancer promotes tumor immune tolerance and results in poor prognosis." (PMID 34034744, 2021). "KM plotter was used to validate the prognostic value of COL3A1, GPR158 and PITHD1 in an external ovarian cancer dataset." (PMID 31533654, 2019). "From this module, COL16A1, COL3A1, and COL1A2 are likely to be ovarian cancer genes, as they are cancer genes and are enriched with at least one pathway containing ovarian cancer genes." (PMID 25611546, 2015). "The expression of COL3A1 in approximately 5 of the liver cancers, DLG3 in 5 of the liver, 7 lung and 5 ovarian cancers, and RN43 in 7 of the colon, 8 ovarian and 5 prostate cancers seemed to have higher expressions than the normal tissues." (PMID 23282184, 2012).